PIK3R4 (phosphoinositide-3-kinase regulatory subunit 4)
Description:
Regulatory subunit of the PI3K complex that mediates formation of phosphatidylinositol 3-phosphate; different complex forms are believed to play a role in multiple membrane trafficking pathways: PI3KC3-C1 is involved in initiation of autophagosomes and PI3KC3-C2 in maturation of autophagosomes and endocytosis. Involved in regulation of degradative endocytic trafficking and cytokinesis, probably in the context of PI3KC3-C2.
Synonyms: VPS15; p150
Tractability: Small molecule: a structure with a bound ligand is known; it belongs to a druggable protein family. PROTAC: ubiquitination databases record sites on it; its protein half-life has been measured; a small molecule that binds it is known.
Target class: Enzyme
Gene: Protein-coding gene on chromosome 3 (130,678,934 to 130,746,829, reverse strand). Ensembl gene ENSG00000196455.
Subcellular location: Late endosome; Cytoplasmic vesicle, autophagosome; Membrane
Subcellular location (Human Protein Atlas): Microtubules; Primary cilium; Vesicles; Basal body; Cytokinetic bridge
Pathways (Reactome):
Disease: Dengue virus modulates apoptosis; SARS-CoV-2 activates/modulates innate and adaptive immune responses; Translation of Replicase and Assembly of the Replication Transcription Complex
Metabolism: Synthesis of PIPs at the Golgi membrane; Synthesis of PIPs at the early endosome membrane; Synthesis of PIPs at the late endosome membrane
Immune System: Antigen Presentation: Folding, assembly and peptide loading of class I MHC; Toll Like Receptor 9 (TLR9) Cascade
Signal Transduction: PI3K Cascade; RHO GTPases Activate NADPH Oxidases
Autophagy: Macroautophagy
Gene Ontology:
Molecular function: protein binding; protein kinase activity; protein serine/threonine kinase activity; ATP binding; protein serine kinase activity
Biological process: autophagosome maturation; early endosome to late endosome transport; phosphatidylinositol 3-kinase/protein kinase B signal transduction; phosphatidylinositol-3-phosphate biosynthetic process; receptor catabolic process; regulation of autophagy; regulation of cytokinesis; regulation of macroautophagy; cellular response to glucose starvation; late endosome to vacuole transport; macroautophagy; pexophagy; protein phosphorylation; protein targeting to lysosome; protein targeting to vacuole
Cellular component: late endosome; membrane; phosphatidylinositol 3-kinase complex, class III; axoneme; cytosol; nucleus-vacuole junction; phagocytic vesicle membrane; phosphatidylinositol 3-kinase complex, class III, type I; phosphatidylinositol 3-kinase complex, class III, type II; autophagosome; cytoplasm
Genetic constraint (gnomAD): Loss-of-function variants: 19 observed, 77.08 expected, observed/expected ratio (o/e) 0.25, 90% interval 0.17 to 0.36. The upper end of that interval is the gene's LOEUF score, 0.36, which puts it in group 1 of 6, group 1 being the genes least tolerant of losing a copy. Missense variants: 881 observed, 1,171.7 expected, observed/expected ratio (o/e) 0.75, 90% interval 0.71 to 0.8. Synonymous variants: 390 observed, 409.81 expected, observed/expected ratio (o/e) 0.95, 90% interval 0.88 to 1.03.
Homologues: Orthologues: chimpanzee PIK3R4 (99% identical), macaque PIK3R4 (99% identical), rabbit PIK3R4 (98% identical), dog PIK3R4 (97% identical), guinea pig PIK3R4 (97% identical), mouse Pik3r4 (96% identical), rat Pik3r4 (96% identical), pig PIK3R4 (89% identical), tropical clawed frog pik3r4 (87% identical), zebrafish pik3r4 (81% identical), Drosophila melanogaster Vps15 (40% identical), Caenorhabditis elegans vps-15 (26% identical).
Diseases named in the same sentence as PIK3R4 in open-access papers:
PIK3R4 is named in the same sentence as 41 diseases in open-access papers, as found by Europe PMC text mining. Sharing a sentence is not in itself a finding about the gene and the disease. The quoted sentences say what the papers report.
ciliopathy (5 papers, 2016 to 2023). A genetic disorder of the cellular cilia or the cilia anchoring structures, the basal bodies, or of ciliary function. "PIK3R4 codes for a protein involved in trafficking and autophagy, and missense mutation of PIK3R4 is linked to ciliopathy." (PMID 37026480, 2023). "PIK3R4 is the candidate gene for UA, which can cause ciliopathies and affect kidney function." (PMID 36575369, 2022). "Here, we report the identification of a mutation in the PIK3R4/VPS15 gene (MIM 602610, NM_014602.2: c.2993G>A, R998Q) in three affected siblings with a ciliopathy phenotype." (PMID 27882921, 2016). "Here, we identify a missense mutation in PIK3R4 (phosphoinositide 3-kinase regulatory subunit 4, named VPS15) in a family with a ciliopathy phenotype." (PMID 27882921, 2016).
melanoma (3 papers, 2012 to 2021). A malignant, usually aggressive tumor composed of atypical, neoplastic melanocytes. "A previous study revealed that somatic mutation of PIK3R4 contributed to melanoma metastasis, and its functions in UM progress are worthy of further study." (PMID 33868366, 2021). "PIK3R4 mutation was discovered in metastatic melanoma, suggested an important function in melanoma." (PMID 31472672, 2019). "Recent studies in melanoma have indicated that some components of the PI3K pathway (PTEN, MTOR, IRS4, PIK3R1, PIK3R4, PIK3R5 and NFKB1) are co-mutated in 17% of BRAF V600E mutant and 9% of NRAS mutant melanomas." (PMID 23006971, 2012).
epilepsy (2 papers, 2024 to 2026). A brain disorder characterized by episodes of abnormally increased neuronal discharge resulting in transient episodes of sensory or motor neurological dysfunction, or psychic dysfunction. "In humans, mutant PIK3R4/VPS15 is associated with epilepsy and atrophy in the cortical region of the brain." (PMID 41277110, 2026).
ovarian carcinoma (2 papers, 2019 to 2025). A malignant neoplasm originating from the surface ovarian epithelium. "Meanwhile, copy number gains of PIK3CA and PIK3R4 were associated with decreased survival in ovarian cancer." (PMID 31472672, 2019). "The results shown that gene MZB1, HSF1, PIK3R4, PSMB9, RSF1 and SPI1were significantly overexpressed in ovarian cancer cells SKOV-3." (PMID 40424327, 2025).
prostate carcinoma (2 papers, 2020). A carcinoma that arises from epithelial cells of the prostate gland. "Of note was PI3K family members: PIK3C2G, PIK3CA, PIK3CB, PIK3R4, Mucin family members: MUC1, MUC4 and MUC6 and other prostate cancer associated genes such as SMAD4, SOX9 and SPOP7,9,40,41." (PMID 32796921, 2020). "Although PIK3C3/PIK3R4 mutation and PIK3C3 gene amplification are infrequent events in prostate cancer (<1% of cases), PIK3R4 high-level gene amplification is observed in up to 6.5% of cases and could potentially facilitate prostate cancer growth." (PMID 32630372, 2020).
Alzheimer disease (1 paper, 2021). A progressive, neurodegenerative disease characterized by loss of function and death of nerve cells in several areas of the brain leading to loss of cognitive function such as memory and language. "The expression levels of NRBF2, along with BECN1, PIK3C3 and PIK3R4, are reduced in Alzheimer disease (AD) post mortem brains." (PMID 33459128, 2021).
breast carcinoma (1 paper, 2020). "The KM plotter analysis points thatsignificant upregulation of ATG3, ATG5, PIK3R4, and ATG8B to be linked with poor prognosis of Tamoxifen treated breast cancer patients." (PMID 34621117, 2020).
colorectal cancer (1 paper, 2019). A primary or metastatic malignant neoplasm that affects the colon or rectum. "In particular, we identified a small set of genes (in particular VRK1, CSNK1A1, and PIK3R4) that were more dramatically depleted in colorectal cancer cell lines, than a range of leukemia, liver and pancreatic cancer cell lines." (PMID 31891587, 2019).
cortical atrophy (1 paper, 2021). "Blunted expression of PIK3R4/VPS15 (phosphoinositide‐3‐kinase regulatory subunit 4) is associated with neurodevelopmental impairment and cortical atrophy, matching the phenotype of patients bearing loss‐of‐function mutations in this gene." (PMID 34459017, 2021).
prediabetes (1 paper, 2025). "miR-192 was up-regulated in obese prediabetes and targeted PIK3R4, ACVR2B, and inflammatory mediators such as TNFα and IL-1β." (PMID 41400625, 2025).
thymic carcinoma (1 paper, 2025). Thymic carcinoma (TC) is a type of thymic epithelial neoplasm characterized by a high malignant potential. "Further analysis found different mutations across multiple PI3K subunit genes in another cell line and several primary thymic carcinoma samples, including two catalytic subunits (PIK3CA and PIK3CG) and another regulatory subunit (PIK3R4)." (PMID 39538003, 2025).
cancer (7 papers, 2012 to 2025). A tumor composed of atypical neoplastic, often pleomorphic cells that invade other tissues. "We found MTOR and CAMKK2 as a feature important to both Luminal B and HER2-enriched cancers, while PIK3R4, a regulatory subunit of PI3K complex, was observed to be significant to TNBC and HER2-enriched cancers within the autophagy module." (PMID 40700427, 2025). "More specifically, both TNBC and HER2-enriched cancers showed a PIK3R4 (a regulatory subunit of PI3K complex), and the HER2 + cancers an MTOR-associated defects of metabolic changes." (PMID 40700427, 2025). "PIK3R4 encodes a regulatory kinase subunit in the PI3K/AKT pathway, a central signalling network that controls cancer cell proliferation, survival, and metabolism." (PMID 38971800, 2024). "The differential expression of PIK3R4 in tumour samples and normal samples from all TCGA cancer types was observed, the results indicated that PIK3R4 is significantly up-regulated in DLBCL, PAAD, and THYM compared to their corresponding normal tissues." (PMID 37670973, 2023). "First, the PIK3R4 expression in DLBCL is positively correlated with immune cell content in the cancer microenvironment." (PMID 37670973, 2023). "Here, we first analyzed the change in PIK3R4 expression in DLBCL tissues using bioinformatics analysis, and PIK3R4 was found to be expressed differently in diverse cancer tissues." (PMID 37670973, 2023). "As a novel member of the autophagy pathway, PIK3R4 plays a crucial role in several malignant tumours progression, but its role and molecular mechanism in DLBCL are unclear." (PMID 37670973, 2023). "More importantly, the expression of PIK3R4 in DLBCL was correlated with the immune cell content in the cancer microenvironment, CD8(+) T-cell and neutrophil infiltration and the levels of several immune checkpoint molecules, including BTN3A2, BTN3A1, PRF1, CXCL9, PDCD1, and TIGIT." (PMID 37670973, 2023). "In particular, the AMPK/MTOR and the canonical AMPK/PI3K/AKT/MTOR cascades were more highlighted in luminal B cancers (by CAMKK2 and MTOR) and in HER2-enriched cancers (by CAMKK2, PIK3R4 and MTOR), respectively." (PMID 40700427, 2025).
tumor (3 papers, 2019 to 2023). "Together, our data suggest that PIK3R4 functions as a novel regulator of immune cell infiltration within the DLBCL tumour microenvironment and is a valuable potential prognostic biomarker for DLBCL patients." (PMID 37670973, 2023). "The median expression value for PIK3R4 in tumour tissues was 21.52 (range 3.72-33.99), while the median level of PIK3R4 in benign lymphadenitis tissues was 11.03 (range 2.47-24.73)." (PMID 37670973, 2023). "In addition, the correlation between the PIK3R4 level and immune infiltration cell-related markers in the tumour microenvironment of DLBCL was determined." (PMID 37670973, 2023). "Then, the somatic copy number alteration (SCNA) module provided the correlations between tumour immune infiltration levels among DLBCL and different SCNAs for PIK3R4 by the Wilcoxon rank-sum test." (PMID 37670973, 2023). "We confirmed some of these genes, including VRK1, CSNK1A1 and PIK3R4, were also essential in a range of other human CRC lines, suggesting that they may represent cell or tumor-type specific vulnerabilities." (PMID 31891587, 2019).
infection (2 papers, 2025 to 2026). The state of being infected such as from the introduction of a foreign agent such as serum, vaccine, antigenic substance or organism. "In our study, TLR5 was downregulated, while PIK3R4 was upregulated, both demonstrating a pro-infection activity." (PMID 40431739, 2025).
PIK3R4 also shares sentences with these, for which no sentence is quoted: lysosomal storage disease (3 papers); metastatic melanoma (2); Atrophy (1); Danon disease (1); diabetes (1); diffuse large B-cell lymphoma (1); dyslipidaemia (1); endothelial dysfunction (1); entropion (1); hepatocellular carcinoma (1); Hydrocephalus (1); Insulin resistance (1); Intellectual disability (1); Kidney Cyst (1); kidney failure (1); leukemia (1); Lysosomal disease (1); metabolic syndrome (1); myopathy (1); neuroblastoma (1); pancreatic cancer (1); Renal cyst (1); retinal degeneration (1); retinitis pigmentosa (1); steatosis (1); vacuolar myopathies (1); viral infection (1).